SMO (smoothened, frizzled class receptor)
Diseases named in the same sentence as SMO in open-access papers (continued):
Sharing a sentence is not in itself a finding about the gene and the disease.
cancer (continued). "Together, these data identify DYRK1B as possible therapeutic target to overcome SMO-inhibitor resistance in GLI1-dependent cancer cells." (PMID 26784250, 2016). "The etiologic role of HH signaling in cancer has triggered numerous efforts to develop HH pathway antagonists targeting the essential HH effector SMO." (PMID 26784250, 2016). "Two direct SMO antagonists, the steroidal natural product cyclopamine and the anti-cancer drug vismodegib, blocked Gli1 activation by MβCD:cholesterol." (PMID 27705744, 2016). "Erismodegib (also known as sonidegib and Odomzo®, East Hanover, NJ, USA) is an orally bioavailable SMO antagonist created by Novartis that has been shown to induce cell cycle arrest and apoptosis in a variety of cancer cell lines." (PMID 26891329, 2016). "SMO inhibition prevents the downstream activation of GLI transcription factors, leading to suppression of those genes associated with cancer growth and progression." (PMID 26891329, 2016). "In this review, the emerging role of Hh signaling in cancer is critically evaluated focusing on the potential of targeting Hh signaling more downstream of SMO, i.e. at the level of the GLI transcription factors." (PMID 26053182, 2015). "Several SMO inhibitors are currently being tested in clinical trials for the treatment of multiple types of cancer." (PMID 26053182, 2015). "Induction of autophagy by SMO inhibitors has also been shown in a variety of other cancer cell lines." (PMID 26106586, 2015). "In some of the cancers active SMO mutant proteins fail to co-localize with PTCH1 thereby allowing the activation of the pathway independently of Hh signaling." (PMID 25985215, 2015). "Results from these clinical trials will address the applicability of SMO inhibitors in combination with other targets in multiple cancer types." (PMID 25660620, 2015). "First, canonical Hh signaling in cancer is quite limited to tumors with gene mutations in PTCH1 and SMO, which will be sensitive to SMO signaling inhibitors." (PMID 26343727, 2015). "Hh pathway inhibition has been proven to be an effective anti-cancer therapeutic strategy, and several antagonists targeting SMO have been developed and show efficacy in preclinical studies and clinical trials in humans." (PMID 23626687, 2013). "BCC, one of the most common human cancers, regularly shows abnormalities of the Hh pathway arising from mutations in PTCH1 (50%), SMO (10%) and other genes, including Su(Fu)." (PMID 23303278, 2013). "These drugs, such as Cyclopamine, Vismodegib etc. are only effective when a cancer cell with excessive Hedgehog pathway activation, is encountering over-expressed hedgehog ligands (SHH, IHH or DHH) or has mutated PTCH1 or SMO in membrane." (PMID 23935937, 2013). "This emphasizes that switching off the GLI genes downstream of SMO, that determines HH-dependent transcriptional gene regulation, is critical in terminating HH-dependent survival in cancer cells." (PMID 23097684, 2012). "In the end, we identified six genes (DLGAP5, DSCC1, SSBP1, UBE2C, SNRPD1, and SMO) with a vital role in prevention of cell death in both cell lines and hence six potential drug targets for silencing in cancer therapy." (PMID 23251412, 2012). "An important consideration is that SMO is localised in the primary cilium of the cell, which is critical in HH signalling and cancer progression." (PMID 23125850, 2012). "Variable activity of SMO inhibitors has been demonstrated in preclinical models and clinically, in a variety of different types of human cancers." (PMID 23097684, 2012). "In other cancer types, SMO inhibitors including GDC-0449, IPI-926 or LDE225, have demonstrated limited clinical activity." (PMID 21860067, 2011). "Several types of human cancers have demonstrated aberrant activation of the HH pathway by ligand-independent signaling such as, amplification of GLI1 or GLI2, mutations in PTCH or SMO, or dysregulated gene expression." (PMID 21860067, 2011).
cancer (continued). "Small molecule inhibitors of SMO have been studied in preclinical models, and applied to the treatment of various types of cancers in humans." (PMID 21860067, 2011). "Cancer stem cell self-renewal is under control by the SHH/SMO/GLI signaling system." (PMID 39900571, 2025). "Drugs targeting SMO, such as vismodegib and sonidegib, which are already used in other cancers, could be evaluated for efficacy in MGs." (PMID 39316249, 2025). "We have shown that inhibiting GLI or SMO re-sensitizes resistant cancer cells to kinase inhibitors." (PMID 40301543, 2025). "Importantly, GLI2 inhibitors effectively suppressed the growth of Smoothened (SMO) inhibitor-resistant hedgehog-driven cancer models." (PMID 40133270, 2025). "These SMO inhibitors are in clinical trials for efficacy in various cancers." (PMID 40869256, 2025). "Later modifications of IPI-269609 yielded saridegib, a potent SMO inhibitor which completely abrogated tumor regrowth in B837Tx medulloblastoma xenograft models following treatment with saridegib, indicating complete elimination of cancer cells." (PMID 38612911, 2024). "Vismodegib (GDC-0449) is an FDA-approved SMO inhibitor targeting SHH-driven cancers." (PMID 36683064, 2023). "The role of SMO has been investigated in many cancers: breast, liver, pancreas and colon." (PMID 37240278, 2023). "Basal cell carcinomas (BCCs), the most common type of human cancer, are known to be caused by activation of the hedgehog pathway, via loss of function mutations of PATCHED-1 (PTCH1) or gain of function mutations of SMOOTHENED (SMO)." (PMID 36864465, 2023). "Previous studies found that the Hh pathway genes, SMO and GLI1, are regulated by bFGF, and the SMO receptor is responsible for maintaining normal embryonic development and that abnormalities in this protein are associated with cancer." (PMID 37139482, 2023). "The HH pathway promotes cancer growth, so novel drugs that antagonize HH signaling components, such as SMO, could prove of therapeutic value." (PMID 37510333, 2023). "In the pan-cancer cohort (n = 1,347), a significant overall survival advantage was observed in patients with SMO mutations [not reached (NR) vs. 18 months, adjusted p = 0.024]." (PMID 36405701, 2022). "However, subsequent clinical trials utilizing SMO antagonists in these cancers have been mostly disappointing, with one exception in the discussion of AML." (PMID 36010600, 2022). "Aberrant Hh activation in cancer can also arise through non-canonical/SMO independent signaling linked to a number of different oncogenic pathways, such as PI3K/AKT, RAS-RAF-MEK-ERK signaling, KRAS constitutive activation, and TGF-beta." (PMID 36358635, 2022). "In the subgroup analysis, the survival advantage of patients with SMO mutations receiving ICI treatment over the SMO_WT patients was prominent and consistent across each subgroup, including age, gender, cancer type, treatment type, and TMB status (all pinteraction > 0.05)." (PMID 36405701, 2022). "We observed an enrichment of the DDR gene mutations in SMO-mutated tumors in the TCGA pan-cancer cohort, the ICI cohort, and the non-ICI cohort." (PMID 36405701, 2022). "Indeed, we also show that interfering for MAPK15 expression strongly reduces the ability of an activated form of SMO to support cancer stem cells self-renewal, while failing to affect the same activity induced by the GLI2 oncogene." (PMID 34638386, 2021). "As several SMO inhibitors are in clinical development for the treatment of cancer, we also evaluated whether targeting AMPK signaling would increase the therapeutic efficacy of these drugs." (PMID 34203724, 2021). "In vitro, 4s was more efficient than vismodegib to induce apoptosis in human cancer cells and that might be attributed to its dual ability to function as a SMO antagonist and apoptosis inducer." (PMID 34445078, 2021).
cancer (continued). "4s shows an anti-proliferative activity, induces cell cycle arrest and apoptosis, and inhibits colony formation of multiple cancer cell types Additionally, we found that 4s promoted the inhibition of genes targeted by the HH signalling pathway, and acts as a SMO antagonist in vitro." (PMID 34445078, 2021). "Hence, this review describes the various SMO-dependent and SMO-independent routes of GLI regulation in the tumorigenesis of multiple cancers in order to provide a holistic view of the paradigms of hedgehog signaling networks involving GLI regulation." (PMID 34572373, 2021). "Lastly, inhibiting the GLI function serves as a promising strategy for blocking both canonical and noncanonical input and may serve as an alternative therapeutic method for treating SMO inhibitor-resistant cancers." (PMID 34572373, 2021). "Several SMO inhibitors, including Vismodegib, Sonidegib and Glasdegib, have been approved successively since their potent activity in repressing Hedgehog signaling and cancer progression." (PMID 34959397, 2021). "Also the evidence that a cancer-prone phenotype of NBCCS fibroblasts was significantly repressed by SMO inhibitors strengthens the use of this class of compound in the management of syndromic patients." (PMID 34831015, 2021). "For other cancer types where mutations in Hh pathway genes are mostly absent, the utility of SMO inhibitors as monotherapy is less profound." (PMID 34572373, 2021). "Furthermore, GLI inhibitors effectively suppress cancer growth in many GLI-dependent cancers that utilize an SMO-independent route of GLI regulation, of which treatment with upstream inhibitors has proven ineffective." (PMID 34572373, 2021). "Hence, we propose that targeting GLI transcription factors shows promise as a therapeutic strategy for overcoming SMO-independent cancers’ growth." (PMID 34572373, 2021). "Current treatment strategies aim to inhibit GLI signaling by targeting SMO in cancer cells." (PMID 34639011, 2021). "However, we do note that similarly high IC50 values of vismodegib have been reported for a number of other cancer cell lines sensitive to SMO knockdown." (PMID 32913560, 2020). "The results indicate that DNA methylation of the SMO gene may play an important role in the development of cancer." (PMID 32784501, 2020). "Moreover, the overexpression of SMO mRNA is present in cancer stem cell CD133+ mouse liver cell line Hepa1-6." (PMID 32962123, 2020). "SMO could affect epithelial–mesenchymal transition, invasion, and migration of cancer stem cells in the pancreas." (PMID 31979397, 2020). "SMO expression was undetectable in 8 of 60 cancer cell lines in the panel." (PMID 32784501, 2020). "A better understanding of the role of SMO in cancer could contribute to the development of novel therapeutic approaches." (PMID 32962123, 2020). "Therefore, down‐regulated miR‐326 is proposed to enhance the cancer‐promoting effects of SMO/Hedgehog signal." (PMID 32743904, 2020). "In addition, SMO inhibitors can suppress cancer formation, reduce the proliferation of cancer cells, trigger apoptosis and suppress cancer stem cell activity." (PMID 32962123, 2020). "The epigenetic regulation of SMO transcription was characterized in 33 cancer cell lines." (PMID 32784501, 2020). "Furthermore, SMO-independent GLI activation has been reported in some cancers, including non-small cell lung cancer and PDAC." (PMID 32859041, 2020). "SMO and SUFU mutations have been reported in a variety of cancers." (PMID 32053600, 2020). "In addition, clinical trials of SMO inhibitors are ongoing in various HH signaling pathway-activating cancers." (PMID 32859041, 2020). "Several other SMO antagonists are in clinical trials for various types of cancers." (PMID 31539380, 2019).
cancer (continued). "The availability of such tools and biomarkers will allow to screen cancer patients and select those showing SMO and GLI activation, increasing the subset of cancer patients who will likely respond to HH-GLI pathway inhibition and to monitor the efficacy of therapy." (PMID 31244888, 2019). "Vismodegib is a specific inhibitor of SMO, whereas Nilotinib is also capable of inhibiting multiple kinases and related pathways that may be important for cancer cell growth and maintenance." (PMID 31539380, 2019). "Therefore, it is very likely that CycT has distinct anti-cancer activities different from other SMO antagonists." (PMID 30723259, 2019). "While several SMO inhibitors are in clinical trials for the treatment of BC and other cancers, these findings suggest SMO inhibitors might fail to eliminate basal-like, CSC-like and EMT cells." (PMID 31027259, 2019). "As the first step, we set out to identify currently unknown anti-SMO activities of approved drugs using in-silico methods and primarily focusing on drugs with established activities against complementary cancer-related pathways." (PMID 31539380, 2019). "In addition to the canonical activation of GLI by the HH-PTCH-SMO route, which is typical of normal cells and ciliated tumors, growing evidence points to a SMO-independent stimulation of GLI activity in cancer." (PMID 31244888, 2019). "In order to further complement our conclusions, we ran MD simulations of SMO and its naturally occurring cancer mutants R6.32 to H6.32 and W7.55 to L7.55 based on the crystal structure of human SMO in the absence of the extracellular CRD and without a crystallization scaffold in IL3 (PDB 4JKV)." (PMID 30737406, 2019). "Since then, an array of SMO antagonists have been developed and tested for cancer treatment." (PMID 30723259, 2019). "Notably, these studies also showed substantial benefit of GANT61 over SMO inhibitors, further confirming critical role of GLIs in cancer." (PMID 29695137, 2018). "At this point, GLI inhibitors could be used as a second line therapy to repress active Hh pathway in SMO-resistant cancer cells." (PMID 29695137, 2018). "We demonstrate a small molecule SMO-HDAC antagonist (IHR-SAHA) retains inhibitory activity for GLI transcription induced by SMO-dependent and -independent mechanisms frequently associated with cancer biogenesis." (PMID 29348431, 2018). "This suggests that the cotargeting of SOX2 and the HH pathway with SMO inhibitors could be a novel therapeutic approach to eradicate resistant cancer cells." (PMID 30558232, 2018). "Cyclopamine, an inhibitor of SMO, has been shown to exert few effects in several cancers, and the mechanism mediating aberrant activation of the Hh pathway in GBC remains unknown." (PMID 30389910, 2018). "Overcoming de novo and acquired resistance to SMO inhibitors is a major challenge in the treatment of HH-associated cancers, underlining the high medical need for HH inhibitors acting independent of SMO." (PMID 26784250, 2016). "Moreover, the crosstalk between the pathways was further supported by evidence that combination treatments of SMO inhibitors and mTOR inhibitors showed synergistic effect on cancer cell inhibition 14,19." (PMID 26218750, 2015). "Erismodegib, a SMO antagonist, induces G1 cell cycle arrest and apoptosis in many of the cancers." (PMID 25985215, 2015). "Taken together, we believe that the unsuccessful clinical trials using SMO signaling inhibitors have revealed novel mechanisms underlying Hh signaling activation in cancer, particularly non-canonical Hh signaling." (PMID 26343727, 2015). "SMO inhibitors are being investigated in clinical trials in a range of advanced cancers." (PMID 25660620, 2015). "For this, additional experiments need to be performed to evaluate the efficacy of IMQ in cancer cells expressing drug-resistant variants of SMO or lacking SUFU, the key negative regulator of GLI." (PMID 25594066, 2014).
cancer (continued). "Several SMO antagonists are in clinical trials for the treatment of various cancers." (PMID 25252859, 2014). "In this context it will also be important to address whether ADORA agonists can overcome current limitations of SMO inhibitors for the treatment of acquired or de novo SMO inhibitor resistant malignancies including cancers with SMO-independent GLI activation." (PMID 25594066, 2014). "In order to identify the alternative pathways or connections present in the hedgehog pathway, which was activating the GLI transcription factors after inhibiting SMO, we calculated the dependency matrices for each cancer scenarios, where only the SMO activations was blocked." (PMID 23935937, 2013). "The proliferation of cancer stem cells could be inhibited by a blockade of the Hedgehog pathway due to the deletion of SMO or (and) Gli1." (PMID 24331293, 2013). "Moreover, to determine the alternative pathways which are still active under drug treatment we refined the model simulation by only inhibiting SMO in three types of cancer scenarios and compared the results with the corresponding Treatment scenarios." (PMID 23935937, 2013). "While loss-of-function mutations in PTCH and gain-of-function mutations in SMO activate HH signaling, acquired mutations in SMO or non-canonical GLI activation render cancer cells resistant to SMO antagonists." (PMID 21860067, 2011). "Consequently, GLI1 and its upstream positive regulator Smoothened (SMO) are important targets of anti-cancer therapy and several SMO-targeted small molecule inhibitors are being evaluated clinically." (PMID 21119888, 2010). "The HH signaling pathway is activated in a variety of human cancers following mutations in genes that regulate canonical HH signaling, including the receptor PTC, and the HH signaling molecule, SMO, and can also be activated via transcriptional up-regulation of the HH ligands." (PMID 20957031, 2010). "A high-throughput screen for inhibitors of SMO ciliary localization and ciliogenesis led to the identification of two ciliogenesis antagonists that disrupt ciliogenesis, inhibit the activation of the HH pathway, and abrogate the proliferation of basal-cell-carcinoma-like cancer cells (BCC)." (PMID 37510333, 2023). "In addition, we summarized the development of SMO inhibitors as targeted cancer therapy." (PMID 35163655, 2022). "In addition, we summarized SMO inhibitors in clinical trials as targeted cancer therapy." (PMID 35163655, 2022). "The bulk of AML cells exhibit primary resistance to SMO inhibition (SMOi), leading some to hypothesize that that clinical activity of SMOi is mediated through modulation of self-renewal and chemoresistance in rare cancer stem cells (CSC)." (PMID 36091167, 2022). "Interestingly, the authors found that combinatorial therapies with CDK inhibitor and a small molecule that inhibited the production of these SMO-activating lipids was able to effectively block cancer cell growth and may help overcome resistance to monotherapy." (PMID 35936751, 2022). "Furthermore, we analyzed the expression levels of SMO in various cancers." (PMID 36405701, 2022). "Additionally, GLI inhibitors are more suitable candidates for treating noncanonical Hh pathway-associated cancers that are not dependent on SMO input for GLI activation (discussed in Section 3.1.1 and Section 3.1.2)." (PMID 34572373, 2021). "Whether this mechanism of SMO regulation is translatable to cancer cells remains to be explored." (PMID 34572373, 2021). "Additionally, we present the latest clinical trial findings for the recent development of Hh inhibitors in cancer treatment and provide a comprehensive review concerning the relevance, limitations, and future perspective of SMO/GLI inhibitors as targeted cancer therapy." (PMID 34572373, 2021). "Thus, targeting SMO is a rational strategy for cancers with abnormal HH signaling status." (PMID 33446260, 2021).